CLDN7 (claudin 7)
Diseases named in the same sentence as CLDN7 in open-access papers (continued):
Sharing a sentence is not in itself a finding about the gene and the disease.
tumor (continued). "Claudin-7 (CLDN7) expression is frequently downregulated in CRC tissues in comparison to a normal colon, and this loss is associated with aggressive tumor features, increased metastasis, and poor patient prognosis." (PMID 41373666, 2025). "Knocking out CLDN7 not only promotes tumor cell proliferation but also disrupts the localization of integrin β-1." (PMID 40687428, 2025). "The collaborative action of the ZEB1/NuRD complex transcriptionally represses the tumor suppressor gene CLDN7, stimulates glycolysis, and facilitates tumor progression." (PMID 39193340, 2024). "The results demonstrated a robust enrichment of ZEB1 and HDAC1 on the promoters of CLDN7 and ANXA7, all of which are implicated in tumor suppression." (PMID 39193340, 2024). "At the same time, Muc1 and Cldn7 expression was statistically significantly higher in the tumor tissue of the SH mice in comparison with the TH mice, which is likely associated with a more severe course of CAC." (PMID 39063041, 2024). "A CLDN7 knockout mice model and colorectal cell lines showed significant tumor growth, tumor cell migration, and inhibition in apoptosis via the SOX-9-mediated Wnt/β-catenin signaling pathway." (PMID 38731853, 2024). "C1 CLDN7+ tumour cells were mainly enriched in ‘Oxidative phosphorylation’, ‘ATP synthesis coupled electron transport’, ‘Mitochondrial ATP synthesis coupled electron transport’ and ‘Aerobic respiration’, which are closely related to cellular energy metabolism." (PMID 38894657, 2024). "In the tumor tissue of the TH mice, an increase in Cldn2 expression was observed, followed by a decrease in Cldn7 and Muc13 expression." (PMID 39063041, 2024). "We included the TNBC population in the TCGA_BRCA dataset to compare the expression of CLDN7 in tumor tissue and normal tissue." (PMID 38124743, 2023). "In recent years, claudin has been increasingly studied, and many claudin proteins, such as claudin-18.2, claudin-4, and claudin-7 have been demonstrated to be ideal targets for tumor therapy." (PMID 36959784, 2023). "In contrast, solid metastatic organoids showed a reduction in EpCAM and Cldn7 levels compared to glandular primary tumor organoids." (PMID 36828915, 2023). "Claudin-7 expression is negatively correlated with the glandular size of the tumor cells, and it is more pronounced in medium and large ductal tumors and well-differentiated tumors." (PMID 36959784, 2023). "Further, RNA-seq transcriptome analyses showed that AR-V7 potentiated several cancerous c-MYC downstream genes and suppressed a tumor suppressor Claudin 7 (Cldn7) that was upregulated by c-MYC overexpression." (PMID 36746917, 2023). "Contradictory findings have been presented by other authors who, based on the IHC technique, demonstrated significantly lower CLDN7 staining intensity in CRC tissue in comparison to adjacent non-tumour tissue." (PMID 38201579, 2023). "We found that, in almost all cases (98.8% in the tumor core and 91.66% in the tumor invasive front), more than 60% of the tumor cells (grade 3) showed a high expression of Claudin-7." (PMID 35740581, 2022). "CLDN7 expression is involved in a variety of activities and is a crucial target for preventing tumor proliferation and invasion." (PMID 36620607, 2022). "In order to evaluate the relation between Claudin-7 expression (in the tumor core, respectively in the tumor invasive front) and clinicopathological parameters, correlations were made using Chi-squared and Fisher’s exact test." (PMID 35740581, 2022). "In this retrospective study, the immunohistochemical assessment of Claudin-7 expression was performed on 84 tumor samples, with histologically confirmed advanced stage CRC (stage IV)." (PMID 35740581, 2022).
tumor (continued). "A discontinuous membranous staining pattern of Claudin-7 was observed mostly in the tumor invasion front." (PMID 35740581, 2022). "DSG2-positve tumor nests contained epithelial junctions marked by claudin 7 and were surrounded by mouse-derived stoma cells and extracellular matrix proteins such as laminin." (PMID 36360292, 2022). "Claudin-7 immunohistochemical expression was evaluated in the tumor core and invasion front of CRCs and correlated with clinicopathological parameters and survival using statistical and AI algorithms." (PMID 35740581, 2022). "In CRC, increased claudin-1 expression results in epithelial-to-mesenchymal transition and metastasis, while claudin-7 functions as a tumor suppressor." (PMID 34571860, 2021). "Cldn7 is also a tumour suppressor in CRC, but the specific regulatory mechanism and up/downstream relationships between the two molecules must be determined in recovery experiments to provide a conservative explanation for these findings." (PMID 34281572, 2021). "Coincident upregulation of both epithelial and mesenchymal genes was observed in the majority of blood-derived CTC samples compared to primary tumour, while a few epithelial genes such as CLDN7, CD24 and CDH1 were downregulated in the CTC samples." (PMID 34206049, 2021). "Trypsin-2 (Try2), a tumor-associated serine proteinase, has been shown to activate pro-membrane type 1 MMP (MT1-MMP), leading to downregulation of claudin-7 and disruption of TJs, which induce tongue carcinoma invasion." (PMID 34354941, 2021). "Cell proliferation assays, migration assays, apoptosis assays, tumour sphere formation assays in vitro, and subcutaneous xenograft models in vivo were used to determine the effects of Cldn7 knockdown on the biological characteristics of CRC stem cells." (PMID 34281572, 2021). "Claudin-7 (Cldn7), a tight junction protein, was recently reported to function as a candidate tumour suppressor gene in CRC." (PMID 34281572, 2021). "In particular, claudin-4 and claudin-7 transcript levels were increased by over 2-fold in normal fallopian tubes compared to tumor samples (both p < 0.001), whereas claudin-3 showed a 1.18-fold increase in fallopian tubes compared to HGSOCs (p = 0.305)." (PMID 32850397, 2020). "For a negative subset of CCRCCs and ROs, very focal (<10%) and mild-to-moderate staining for CK7 or Claudin-7 was also appreciated in some tumor cells that are usually located on the wall of cystic structures or within sclerotic/edematous stroma." (PMID 31737127, 2019). "For both MMP2 and COL5A, the mRNA levels in HPV-positive tumor samples were significantly reduced, whereas the levels of CLDN7 were increased." (PMID 30918060, 2019). "Using combined data from human patients and in vitro and in vivo analyses in ccRCC cells manipulated for CLDN7 overexpression, we previously demonstrated a tumor suppressing role of CLDN7 and that it induced epithelial features in ccRCC cells." (PMID 30428910, 2018). "Added to the growing complexity, it has been demonstrated recently that claudin-7 to be a tumor promoter, in colon and pancreatic cancer, through its association with epithelial cell adhesion/activating molecule (EpCAM) thereby promoting/inducing EMT." (PMID 30728783, 2018). "We have demonstrated a previously undescribed role of CLDN7 as a ccRCC suppressor and suggest that loss of CLDN7 potentiates EMT and tumor progression." (PMID 30428910, 2018). "Mouse model experiments were performed to confirm the effects of CLDN7 on tumor growth and metastasis in vivo." (PMID 30428910, 2018). "Lastly, WB showed that Claudin 1, Claudin 4, and Claudin 7 were closely related to tumour growth and metastasis." (PMID 28376864, 2017). "Further more, the WB results proved that the Claudin 1, Claudin 4, and Claudin 7 proteins were closely related to the mechanism of tumour growth and metastasis." (PMID 28376864, 2017).
tumor (continued). "The present study aimed to evaluate the expression of CLDN1 and CLDN7 under different cell differentiation status, and their relationship to tumor progression in NPCs." (PMID 28055967, 2017). "Claudin 1, Claudin 4, and Claudin 7 were the main proteins contributing to the oridonin anti-tumour effect based on the inhibition of angiogenesis." (PMID 28376864, 2017). "Initially, two studies found that both primary CRC, as well as metastases, showed overexpression of claudin-7, the metastases in one study showing somewhat lower expression compared to the primary tumor." (PMID 26243458, 2016). "Genes associated with cell-cell adhesion (claudin-7, CD166) were significantly downregulated, indicating a more metastatic phenotype of CTCs compared to bulk tumor cells derived from hepatic metastases." (PMID 27029058, 2016). "Loss of claudin-7 expression was associated with the high pathologic grade advanced TNM staging, large tumor size, the presence of microscopic perineural and vascular invasions and regional lymph node involvement." (PMID 27398181, 2016). "Only loss of claudin-7 expression was associated with the high pathologic grade, advanced TNM staging, large tumor size, the presence of microscopic perineural, vascular invasions and regional lymph node involvement." (PMID 27398181, 2016). "Downregulation of claudin-7, a protein involved in cell-cell adhesion, also fits well into this observation, indicating a more metastatic phenotype of CTCs compared to bulk tumor cells." (PMID 27029058, 2016). "Several DEGs have been demonstrated to be associated with tumor development, including protease serine 8 (PRSS8), claudin 7 (CLDN7) and Ras-related protein Rab-25 (RAB25)." (PMID 25351113, 2015). "Six control tumors grew significantly slower than their paired claudin-7 KD tumors and the slopes of these paired tumor growth curves are significantly different." (PMID 26081244, 2015). "Antisense knockdown of either EpCAM or claudin-7 reduces tumor growth and metastasis in mice, and knockdown of both is more effective." (PMID 24885350, 2014). "In breast cancer, claudin-7 expression was not only found to be decreased but also to be inversely correlated with tumor grade and metastatic disease." (PMID 23685873, 2013). "Low levels of claudin-7 were correlated with a late tumor stage (P=0.023) and low histological grade (P=0.018)." (PMID 23946785, 2013). "Moesin (MSN), a member of the ezrin-rdixin-moesin family and Claudin7 (CLDN7), a tight junction protein, both play a role in tumor cell metastasis." (PMID 22272721, 2012). "The tight junction proteins Claudin 1 and Claudin 7 were stained immunohistochemically in the tumor and in the surrounding normal mucosa." (PMID 23675182, 2010). "This reinforces CLDN7’s importance as a brake on tumor progression." (PMID 40687428, 2025). "This highlights the possibility that, under certain regulatory conditions, CLDN7 could contribute to tumor aggressiveness, underscoring the context-dependent nature of claudin function." (PMID 40687428, 2025). "As in colon and lung, CLDN7 appears to act as a tumor suppressor in the endometrium." (PMID 40687428, 2025). "Claudins like CLDN7 can act as tumor suppressors in one tissue but oncogenes in another." (PMID 40687428, 2025). "After cellular annotation of the 6 tumour cell types based on marker gene expression, we were able to identify the following: C0 PSCA+ tumour cells, C1 CLDN7+ tumour cells, C2 UBE2C+ tumour cells, C3 MUC6+ tumour cells, C4 CHGA+ tumour cells and C5 MUC2+ tumour cells." (PMID 38894657, 2024). "CLDN7 expression has also been found to correlate with the degree of tumor differentiation." (PMID 38540693, 2024). "Thus, CLDN7 can simultaneously play both tumor-promoting and inhibitory roles in human malignancies, depending on the type of tumor." (PMID 39175074, 2024).
tumor (continued). "The presented results indicate the significant correlation between the CXCL12, CXCR4, CXCL8/CXCR2, M-CSF, MMP-2, MMP-9 ADAM17, ADAMTS-6, and CLDN7 levels and tumor stage, as well as the clinicopathological parameters of OC, such as the presence of lymph node and/or distant metastases." (PMID 38673838, 2024). "In conclusion, these results suggest that CLDN7 may play a critical role in the regulation of tumor immune-microenvironment." (PMID 39175074, 2024). "Moreover, CLDN7 was shown to have a similar tumor-inhibitory effect in oral squamous cell carcinoma." (PMID 38731853, 2024). "In summary, our findings demonstrate that the ZEB1/NuRD complex collaboratively suppressed the transcription of the tumor suppressor gene CLDN7, promoted glycolysis, and exerted an impact on tumor development, potentially signifying the discovery of novel CRC biomarkers." (PMID 39193340, 2024). "Conversely, tumour cells designated as C1 CLDN7+ displayed the highest CNVscore." (PMID 38894657, 2024). "In TH mice, CAC was characterized by a decrease in Muc13 and Cldn7 expression and an increase in Cldn2 expression in the tumor tissue of the distal colon in comparison with the control group, while the expression of Muc13 and Cldn7 in the peritumoral area was higher relative to the tumors." (PMID 39063041, 2024). "Only GEM-located claudin-7 (palmitoylation) promotes tumor cell metastasis." (PMID 36959784, 2023). "In addition, the abnormal destruction of CLDN7 function is one of the important mechanisms for malignant tumor cells to break away from the primary cancer tissue and cause distant invasion and metastasis." (PMID 38124743, 2023). "Increased claudin-7 was also correlated with high tumor stages." (PMID 37686483, 2023). "Moreover, CLDN7 expression levels were significantly reduced or undetectable in metastatic tissue compared with primary tumour tissue." (PMID 38201579, 2023). "Furthermore, significant correlations have been found between CLDN7 expression, lymphovascular and neurotropic invasion, lymphocyte status, and tumour grade." (PMID 38201579, 2023). "Yet, another reason for the tumor-suppressor role played by claudin-7 in the colorectum may be related to the anti-inflammatory role played by this tight junction protein." (PMID 37627123, 2023). "The authors concluded that an enhanced expression of CLDN7 may contribute to tumour-forming ability in vivo." (PMID 38201579, 2023). "The present study identified a significant correlation between Claudin-7 intensity in the tumor invasive front and tumor leukocyte infiltrate (p = 0.033), implying that a decrease in Claudin-7 intensity in the tumor invasive front is associated with an increase in leukocyte infiltrate." (PMID 35740581, 2022). "The Kaplan–Meier univariate survival analysis showed that the immunohistochemical overexpression of Claudin-7 in the tumor invasive front may represent a poor prognostic factor in advanced stages of CRCs." (PMID 35740581, 2022). "Expression of Claudin-7 was defined as the presence of membranous staining in tumor cells." (PMID 35740581, 2022). "CLDN3, CLDN4 and CLDN7 were expressed at an abnormally high level in tumor cells and IM cells." (PMID 35999201, 2022). "By contrast, from a statistical point of view, the study showed that immunohistochemical intensity overexpression of Claudin-7 in the tumor invasive front may represent a poor prognostic factor in the advanced stages of CRCs." (PMID 35740581, 2022). "Therefore, this study was designed to clarify the effect of Cldn7 on the stemness properties of cells in the large intestine, tumour cell proliferation and the specific mechanism that promotes tumourigenesis." (PMID 34281572, 2021). "Also, claudin-7 knockdown cells displayed decreased tumour growth and impaired migration and motility, due to the recruitment of EpCAM with claudin-7." (PMID 32091301, 2020).
tumor (continued). "In addition, in patients with reduced expression of claudin-7 assessed by IHC, we observed a pattern of discontinuous membranous staining indicative of a discohesive architecture that can trigger the release of tumor cells from the primary site." (PMID 32850397, 2020). "Besides, the low expressions of CLDN7 are related to tumor progression and high overall survival rates in patients with ChRCC." (PMID 31998788, 2020). "CLDN7 may serve as a functional tumor suppressor in tumor progression and a potential biomarker and target in patients with ccRCC." (PMID 30428910, 2018). "In this study, we confirmed that downregulation of CLDN7 due to hypermethylation may help predict aggressive tumor status and poor prognosis in ccRCC patients." (PMID 30428910, 2018). "Taken together, it is suggested that CLDN7 may have a fundamental role in tumor progression in ccRCC, by downregulating genes in pathways relating to cancer and EMT at the transcriptional level." (PMID 30428910, 2018). "CLDN7 can help predict aggressive tumor status and poor prognosis in ccRCC patients." (PMID 30428910, 2018). "Interestingly, the results suggest that several pathways relating to cancer and TGF-β, WNT, Focal adhesion and NOTCH pathways relating to epithelial-mesenchymal transition (EMT) and tumor progression were all decreased in ccRCC with high CLDN7 mRNA expression." (PMID 30428910, 2018). "Finally, given the suppressive role of CLDN7 during the process of EMT induced by TGFB1 and Musashi-2, it is a novel strategy to inhibit tumor progression by increasing CLDN7 expression." (PMID 30428910, 2018). "Finally, our research showed that Claudin 1, Claudin 4, and Claudin 7 were closely related to tumour growth and metastasis." (PMID 28376864, 2017). "Also, in order to clarify its role in tumor progression, the role of claudin-7 in esophageal squamous cell carcinoma was analyzed." (PMID 27547510, 2016). "To determine whether this trend is also observed in human PDAC, we performed IHC on primary human PDAC tumours, gross liver metastases and microscopic liver metastases for CLDN7 and FSP1 (n=6 cases)." (PMID 27628423, 2016). "Results proposed that the reduced expression of claudin-7 could lead to tumor progression and subsequent metastatic events." (PMID 27547510, 2016). "In addition, reduced expression of claudin-7 corresponds to a higher tumor grade as well as metastatic disease." (PMID 27547510, 2016). "Significantly, loss of claudin-7 expression was associated with the high pathologic grade (P=0.027), advanced TNM staging (P=0.00), large tumor size (P=0.01), the presence of microscopic peri-neural (P=0.01) and vascular (P=0.031) invasions and regional lymph node involvement (P=0.001)." (PMID 27398181, 2016). "This evidence indicates that CLDN7 may promote tumor development by disrupting the cell adhesion process." (PMID 25351113, 2015). "The tumor induced by control cells was much smaller than that induced by claudin-7 KD cells." (PMID 26081244, 2015). "EpCAM also associates with the tight junction protein, claudin 7, to promote tumor cell migration rather than cell-cell adhesion that leads to lymphatic spread." (PMID 24885350, 2014). "Other claudins that were up-regulated in the tumor samples were CLDN2 and CLDN7, and these genes might also be implicated in gastric carcinogenesis." (PMID 24321518, 2013). "Interestingly, TM4 and the MMTV-neu tumor had ratios of claudin 7 to cytokeratin less than one-eighth of that in the slower-growing TM10 line." (PMID 15743505, 2005). "This suggests that the high expression of CLDN7 may help tumor drug resistance." (PMID 38124743, 2023).